TWIST1 (twist family bHLH transcription factor 1)
Diseases named in the same sentence as TWIST1 in open-access papers (continued):
Sharing a sentence is not in itself a finding about the gene and the disease.
tumor (continued). "ID4 is a potential tumor suppressor and suppresses MMP2-mediated invasion of glioblastoma-derived cells by direct inactivation of TWIST1." (PMID 30899759, 2019). "The ability of RUNX2 to enhance the metastatic potential of tumor cells is largely based on its ability to regulate genes crucial to tumor progression including VEGF, MMP9, MMP13, OPN, SNAI 1–2, TWIST1 and TIMP13." (PMID 31395086, 2019). "Levels of miR-15a-3p and Twist1 mRNA in two types of tissues (SCLC and non-tumor) were measured and compared by qPCR and paired t test, respectively." (PMID 31842825, 2019). "In summary, this study described for the first time that TP was transcriptionally regulated by Twist1 and that TP activity promoted HCC metastasis and VM formation through the pentose Warburg effect under a deteriorated tumor microenvironment." (PMID 30674871, 2019). "Tumor volume and weight of CNE-1 xenografts at four weeks after implantation were dramatically inhibited by knocking-down of Src-1 or Twist1." (PMID 30973923, 2019). "Along with the oncosuppression induced by the formation of complexes of TWIST1 with other epigenetic regulators, the acetylated SPZ1–TWIST1 complex activates VEGF expression, thus inducing changes in tumor cells and the tumor microenvironment." (PMID 30154425, 2019). "Some studies showed that Twist1 is a highly important transcription factor in EMT, and the overexpression of Twist1 induces EMT, which is a key process in tumor metastasis." (PMID 31431619, 2019). "A plethora of studies reported that siRNAs against TWIST1 delivered by nanoparticles inhibited the EMT process in several tumors, leading to the reduction of tumor progression and metastasis and sensitizing cancer cells to chemotherapy drugs and radiotherapy." (PMID 31861725, 2019). "ZEB1 cooperates with TWIST1 for their oncogenic properties, while ZEB2 and Slug work together for tumor-suppression." (PMID 31275381, 2019). "In AC, miR-9-5p exerts a tumor suppressive role and the EMT phenotype is achieved by low levels of miR-9-5p, which enable the upregulation of CDH2 via TWIST1." (PMID 31888045, 2019). "Biologic effect of Src-1 and Twist1 in NPC cell lines was evaluated by western blot, colony formation assay, soft agar assay, scratch wound healing assay, transwell invasion assay and tumor xenografts growth." (PMID 30973923, 2019). "Similar correlation analysis was conducted for mRNA expression datasets for OMA1 and mesenchymal marker genes such as TWIST1, ZEB1, and Fibronectin (FN1) using the input, TCGA_Tumor (BRCA Tumor) and TCGA_Normal (BRCA_Normal) with Pearson’s statistical test." (PMID 31611601, 2019). "Since FN is a major EMT marker expressed by tumor cells and can be upregulated by transcription factors, e.g., Twist1 or Snail1, the role of EMT in formation of FNhigh tumor dormancy at distant sites has been evidenced." (PMID 31861892, 2019). "PRMT1 expression in tumor tissue was compared to the IHC expression of EMT-related transcription factors (ZEB1, RUNX1, and TWIST1) and cell surface markers (ß-catenin, N- and E-cadherin)." (PMID 31655611, 2019). "The main factors that correlate with the embryonic mesenchymal state, tumor metastases and progression include HLA-G, HSP70, hypoxia, STAT3, CD44, SNAIL1, TWIST1, PRRX1, TGFb, WNT/bCAT, ID, and MMPs." (PMID 30899759, 2019). "Tsai and colleagues demonstrated that while expression of Twist1 is required for EMT and tumor dissemination at distant sites, Twist1 repression was indispensable for DTCs outgrowth." (PMID 30258818, 2018). "VEGF, VEGFR1, HIF-1α, TWIST1 and MVD expression was heterogeneous for intensity and expression patterns in the different tumor samples examined." (PMID 29716631, 2018). "TWIST1 is involved in EMT, metastasis, and angiogenesis, and previous studies have shown that vaccination against TWIST1 decreases murine tumor growth and spontaneous metastasis." (PMID 29721396, 2018).
tumor (continued). "Based on our aggregated results, we propose a working model that disruption of ETV6 contributes to tumor progression and TKI-resistance through derepression of TWIST1 and activation of EGFR-RAS signaling." (PMID 29455655, 2018). "Twist1 overexpression reversed the effect of Sox6 on inhibiting EMT, confirming that the effect of Sox6 on suppressing tumour invasiveness is mediated by the modulation of Twist1 expression." (PMID 29369542, 2018). "We extracted total RNA from the mouse tumour tissues, and the qRT-PCR assay results suggested that the ZEB1 and Twist1 expression levels were reduced." (PMID 30518916, 2018). "TWIST1 is a basic helix-loop-helix transcription factor that contributes to carcinogenesis by triggering EMT, thereby influencing tumor invasion behavior." (PMID 29716631, 2018). "Some results suggest that twist-related protein 1 (TWIST1)- and epithelial–mesenchymal transition (EMT)-driven increases in Akt activation, and thus tumour cell proliferation, as a potential mechanism of drug resistance in epithelial ovarian cancer." (PMID 30563166, 2018). "Immunofluorescence was employed to evaluate the cellular location of Twist1 and PAR1 in tumor cells and determine how PAR1, as one of the G protein-coupled receptors (GPCRs) on the cell surface, promotes EET through Twist1." (PMID 30081924, 2018). "Twist1 is a basic helix-loop-helix domain-containing transcription factor that inducing EMT and promoting tumor metastasis." (PMID 30158543, 2018). "Several multipotent TFs, such as Twist1/2, Snail1/2 and Zeb1/2 play key roles in the regulation of EMT program and tumor metastasis." (PMID 30038287, 2018). "Twist1 activity is regulated by the protein kinase Akt1, a member of the highly conserved Akt/PKB serine-threonine kinase family, known to promote tumor initiation and progression." (PMID 30463358, 2018). "Our results support a model that the EGFR facilitates tumor malignancy by reducing ETV6, which enhances TWIST1 activities." (PMID 29455655, 2018). "Very consistently, there are elevated anti-tumor molecules such as perforin, granzyme B, CTSE and increased Th1 transcription factor T-bet while decrease of Th1 inhibitory molecule like SOCS1 and Twist1 in the lung of CD4-Chi3l1 KO mice." (PMID 29403003, 2018). "Positive expression of MACC1, CD44, and Twist1 was found to be positively correlated with invasion, tumor grades, and lymph- node-metastasis (LNM) stages and tumor-node-metastasis (TNM) stages for patients with CAC." (PMID 30021598, 2018). "The signals from primary tumor associated stroma such as TGF-β1 may trigger changes in cytoskeleton reorganization and lead to the activation of nuclear transcription factors, ZEB1, TWIST1 and TWIST2, which, once activated, implement EMT program and promote invasiveness." (PMID 29337896, 2018). "Our results showed that KCTD12 decreases the cell migration of ESCC cells through TWIST1 and can be introduced as a therapeutic marker against the EMT process and tumor relapse." (PMID 30157793, 2018). "Bmi1, a polycomb‐group protein that maintains self‐renewal, is directly regulated by Twist1, which links EMT to tumor‐initiating ability." (PMID 28649800, 2017). "The Bcl-2/Twist1 complex, compared to either Bcl-2 or Twist1 alone, is more efficient in promoting EMT and tumor metastasis in OSCC." (PMID 28032603, 2017). "In this study, we evaluated the expression of Twist1 and CAF markers in 169 human ESCC samples and 20 adjacent non-tumor samples using immunohistochemical staining on tissue microarray slides." (PMID 29029429, 2017). "Hallmarks of EMT include Slug, Snail and Twist1, which play vital roles in EMT transformation and enhance tumor metastasis." (PMID 28035069, 2017). "Twist1 expression rates in stromal fibroblasts were significantly higher in ESCC (152/169, 89.9%) than in adjacent non-tumor esophageal epithelial stroma (8/20, 40.0%) (χ2 = 34.338, P < 0.001)." (PMID 29029429, 2017).
tumor (continued). "Maintenance of the motile phenotype in invading tumor cells depends on weaker but more widely expressed repressors Slug, E47, and SIP1 while Twist1 plays a key role in distant metastasis." (PMID 27902484, 2017). "Twist1 is a transcription factor that is involved in progression of EMT and tumor metastasis in CRC." (PMID 28035069, 2017). "Twist1 expression was necessary and sufficient for CAF activation, and silencing its expression in CAFs inhibited their tumour‐promoting properties." (PMID 28544627, 2017). "In the early stages of MBC, EMT-TFs, like TWIST1, ZEB1/2, and SLUG, repress E-cadherin and β-catenin expression; promote EMT, cell motility and invasiveness; and permit the intravasation of tumor cells." (PMID 28423483, 2017). "We observed that miR186 overexpression significantly decreases the Twist1 protein level in LT-BPH1, M12 and PC3, which provided crucial insight into miR186 executing tumor-suppressing function by directly targeting Twist1 in malignant PCa cells." (PMID 28394356, 2017). "In the tumour microenvironment of mammary xenografts, mesenchymal CD44 expression contributes to the acquisition of an activated fibroblast phenotype via Twist1 activation." (PMID 28544627, 2017). "In other words, the present study supported that the Bcl-2/Twist1 complex, compared to either Bcl-2 or Twist1, is more efficient in promoting EMT and tumor metastasis in OSCC." (PMID 28032603, 2017). "Twist1 was mainly expressed in the nuclei and cytoplasm while VHL was located in cytoplasm in tumor tissue." (PMID 28710479, 2017). "IHC staining of miR-3656 tumor sections confirmed reduced RHOF, increased epithelial marker E-cadherin and reduced expression of the mesenchymal markers TWIST1 and Vimentin." (PMID 29048402, 2017). "Twist1 in turn activates Bmi1, and both of them are essential for promoting EMT and tumor‐initiating capacity." (PMID 28649800, 2017). "VIM, TWIST1, AKT2, and SNAI1 are expressed in CRC pathological tissues, where they promote tumor metastasis by inducing the EMT process." (PMID 28030836, 2017). "We observed substantially improved survival with high lifetime prediagnostic RPA in women with a tumor-methylated APC, CCND2, HIN1, or TWIST1 gene promoter compared with active women with unmethylated gene promoters." (PMID 28222775, 2017). "Because Twist1 is known to be a master regulator of cell migration and metastasis and STS is capable of inducing Twist1 expression, the effect of STS on tumor cell motility was investigated using the scratch wound assay and the Boyden chamber invasion assay." (PMID 28977889, 2017). "MiR-675 promotes tumor progression by suppressing the expression of target genes including Rb, RUNX1, TGFBI, and Twist1." (PMID 29088808, 2017). "First, an IHC assay was performed to assess the expression of Bcl-2, Twist1 and EMT-related proteins in 82 OSCC tumor tissues and 24 para-neoplastic tissues." (PMID 28032603, 2017). "TWIST1 is one of the master regulators of morphogenesis and plays an essential role in EMT and tumor metastasis." (PMID 27412325, 2016). "Similar effects were also observed in vivo on tumor xenografts, wherein PAC increased the expression of E-cadherin and repressed N-cadherin, vimentin, AKT and Twist1." (PMID 27465411, 2016). "Twist1, an important regulator of epithelial-mesenchymal transition (EMT), has been shown to mediate tumor metastasis and induce tumor angiogenesis." (PMID 26823670, 2016). "A lower threshold of ZEB1 or TWIST1 is sufficient to induce stemness and tumor initiation, whereas further induction is necessary for EMT induction, invasion, and tumor metastasis." (PMID 27596438, 2016). "Twist1 is well known to induce epithelial-mesenchymal transition (EMT) and promote tumor metastasis." (PMID 27027434, 2016). "Here we also attempted to investigate the expressive levels of Twist1 and BMI1 in 188Re-liposome treated HNSCC tumor using real-time qPCR." (PMID 27588466, 2016).
tumor (continued). "In our EOC model, we found that sustained TWIST1 overexpression in EOC cells with a mesenchymal phenotype led to enhanced cell survival and proliferation, both in the in vivo tumour engraftment assays and in the presence of cisplatin in vitro." (PMID 27876874, 2016). "Twist1, a bHLH transcription factor, is a prototypical EMT inducer and a major regulator of invasion, metastasis, cancer stemness, and tumor initiation." (PMID 27402962, 2016). "Here we again observe extensive TWIST1 and TWIST2 staining in stromal cells within the main tumor body." (PMID 25528769, 2015). "HMGA2, Twist1 and ZEB1 expressions were significantly higher in samples with poor prognosis with stage IV tumor expressing highest levels of HMGA2, Twist1 and ZEB1." (PMID 25868853, 2015). "Accordingly, transcript levels for seven of these genes were evaluated, with five of them (MEIS1, HOXA3, OTX2, TWIST1, and PROM1) being underexpressed in the tumor samples." (PMID 25908946, 2015). "In this study, we used immunohistochemistry to study the expression of a panel of transcription factors (TWIST1, SNAI1/2, ZEB1 and ZEB2) and other genes intimately related to EMT (CDH1 and LAMC2) at the invasive tumor front of OSCC tissues." (PMID 26214683, 2015). "We observed correlation between TWIST1 and SLUG expression in tumor stroma (Spearman rho’ = 0.37; p = 0.0003)." (PMID 26194471, 2015). "Firstly, we show that TWIST1 and TWIST2 protein expression are found nearly exclusively in the tumor stroma." (PMID 25528769, 2015). "Similar to Twist1 staining, p-4E-BP1 was localized in the nucleus and cytoplasm of cells, but was restricted to tumor glands, as observed by IHC staining." (PMID 26360779, 2015). "The activities of the transcription factors Twist1/2, SNAI1/2, AP1, NF-κB, and Stat3 were suppressed by doxycycline, which reversed EMT and inhibited signal transduction, thereby suppressing tumor growth and metastasis." (PMID 26512779, 2015). "TWIST1 and TWIST2 promoter methylation and protein expression were investigated in six cell lines and further correlated with tumor budding in patient cohort 1 (n = 185)." (PMID 25528769, 2015). "MED30 induced the expressions of EMT-related genes (N-cadherin; CDH2, P-cadherin; CDH3, twist related protein 1 and 2; TWIST1/2, vimentin; VIM), but inhibited the expression of E-cadherin (CDH1) a known tumor suppressor." (PMID 26110885, 2015). "It's now well accepted that TWIST-1, which may function as a multifunctional proto-oncogene during tumorigenesis and progression of solid tumors, protects cells from chemotherapy-induced apoptosis and senescence and promotes tumor epithelial-mesenchymal transition." (PMID 26023795, 2015). "It has been reported that HIF-1 and p65 transcriptionally activate TWIST1 expression to mediate hypoxia-induced and tumor necrosis factor alpha (TNF-α)-induced EMT and tumor metastasis, respectively." (PMID 25848863, 2015). "Consistent with the negative regulation of FOXF2 on the transcription of TWIST1, TWIST1 mRNA levels inversely correlate with the FOXF2 mRNA levels in TNBC tumor (Spearman’s rho = −0.421, P = 0.013)." (PMID 25848863, 2015). "TWIST1 is recognized as a critical modulator in EMT, and its overexpression is able to trigger EMT phenotype and tumor metastasis." (PMID 25848863, 2015). "Lastly, another significant gene resulting positively modulated in the adipogenesis profile during the HCV infection is Twist1, which is able to induce the Epithelial-Mesenchymal Transition (EMT) HCV-related neoplastic transformation and tumor progression." (PMID 24658135, 2014). "Thus, TWIST1 may play an important role in the tumor progression of BNHL." (PMID 25289047, 2014). "Twist1 also is expressed in invasive carcinoma and promotes endothelial-to-mesenchymal transformation (EMT) and metastasis of tumor cells through regulation of genes involved in differentiation, adhesion, and proliferation." (PMID 25262113, 2014).
tumor (continued). "Androgens repress the expression of TWIST1 via NKX3-1, which is a prostate–specific tumor suppressor that is down-regulated in the majority of metastatic prostate tumors." (PMID 23368843, 2013). "In other tumor models, EGF was shown to trigger an EMT with up-regulation of either SNAI1 or TWIST1 possibly through STAT3 activation." (PMID 22272264, 2012). "Twist1 and Bmi1 were mutually essential to promote EMT and tumor-initiating capacity by up-regulating stem cell factors and by repressing the expression of both E-cadherin and p16INK4a." (PMID 21643534, 2011). "Since it is understood that Twist1 and Sox2 regulate the metastatic ability of tumor cells and their involvement in stemness preservation, we analyzed the hUCBSC co-culture treated GSC for Sox2 and Twist1 expression." (PMID 22184289, 2011). "The highest expression of SNAI2, TWIST1, VIM and lowest expression of CDH1 was found in the CCND1low/ID1high subgroup of tumours (yellow bars)." (PMID 21955753, 2011). "The mesenchymal antigen VIM and the transcriptional factor TWIST1 were upregulated in JCK and SCK cells by tumor dedifferentiation." (PMID 21333016, 2011). "A group of transcription factors, including Twist1, Snai1, Snai2, Zeb1, and Zeb2, play key roles in driving EMT during tumor metastasis." (PMID 21725138, 2011). "We investigated the co-regulatory role of Sox2 and Twist1 in GSC and their combinatorial effect on stemness maintenance and tumor progression." (PMID 22184289, 2011). "Moreover, it has been observed that transfection of Bel7402 (highly expressing Twist1) cells with Twist1 shRNA plasmid resulted in suppression of Twist1 expression and subsequent inhibition of cell invasion and migration in vitro, indicating its possible role in tumor cell plasticity." (PMID 22184289, 2011). "Ectopic expression of PRDM5 inhibited tumor cell clonogenicity, at least partially through antagonizing WNT/β-catenin signaling and oncogene expression such as CDK4, TWIST1, and MDM2." (PMID 22087297, 2011). "High expression of Twist1 and Sox2 was observed in the necrotic regions of U251 and 5310 GSC induced tumor, while hUCBSC-treated U251 and 5310 xenografts showed reduced or no expression of either Twist1 or Sox2 in individual experiments." (PMID 22184289, 2011). "Up-regulation of VAV3 and TWIST1 oncogenes and repression of the DKK3 tumor-suppressor was observed in PC346DCC, suggesting a potential AR bypass mechanism." (PMID 20976069, 2010). "Upon moderate hypoxic conditions epithelial tumor cells undergo EMT, which is transcriptionally regulated by Hif-1alpha and its downstream target Twist1; conversely, hyperbaric oxygen treatment triggers a reversed process, MET." (PMID 20730114, 2010). "Based on these findings we propose targeting TWIST1-mediated mesenchymal change as a therapeutic strategy with potential to inhibit GBM invasion and tumor growth, and enhance treatment responses." (PMID 20646316, 2010). "Research has shown that TWIST1, as a transcription factor, can upregulate MAGEA4 expression by indirectly binding to the E-box regions of the MAGEA4 promoter sequence, thereby participating in tumor regulation." (PMID 39905312, 2025). "Via a TWIST1-mediated mechanism, MAO-A activates Sonic hedgehog (Shh) signaling in malignant prostate cells, initiating a cross-talk with the surrounding osteoblasts to promote growth advantages for tumor cells in the bone microenvironment." (PMID 39714760, 2025). "Importantly, the mentioned study demonstrated that the genetic downregulation of ZEB1 and Twist1 leads to a substantial decrease in invasion and growth in selected UVM cell lines, highlighting their indispensable roles in tumor progression." (PMID 40362553, 2025). "Conversely, the enforced expression of TWIST1 increased its dissemination in vivo and migration in vitro in a mouse MM cell line, but did not exert its influence on proliferation and tumor growth." (PMID 39941895, 2025).